HLA-DMB (major histocompatibility complex, class II, DM beta)
Description:
Plays a critical role in catalyzing the release of class II-associated invariant chain peptide (CLIP) from newly synthesized MHC class II molecules and freeing the peptide binding site for acquisition of antigenic peptides. In B-cells, the interaction between HLA-DM and MHC class II molecules is regulated by HLA-DO.
Synonyms: RING7; D6S221E
Tractability: Antibody: UniProt predicts a signal peptide or a membrane-spanning region.
Gene: Protein-coding gene on chromosome 6 (32,934,629 to 32,941,054, reverse strand). Ensembl gene ENSG00000242574.
Subcellular location: Late endosome membrane; Lysosome membrane
Subcellular location (Human Protein Atlas): Vesicles
Pathways (Reactome):
Immune System: MHC class II antigen presentation
Gene Ontology:
Molecular function: MHC class II protein complex binding; protein binding; peptide antigen binding
Biological process: antigen processing and presentation of exogenous peptide antigen via MHC class II; MHC class II protein complex assembly; peptide antigen assembly with MHC class II protein complex; positive regulation of T cell activation via T cell receptor contact with antigen bound to MHC molecule on antigen presenting cell; positive regulation of T cell proliferation; positive regulation of immune response; positive regulation of T cell activation; antigen processing and presentation; immune response
Cellular component: late endosome membrane; lysosomal membrane; MHC class II protein complex; membrane
Genetic constraint (gnomAD): Loss-of-function variants: 16 observed, 22.43 expected, observed/expected ratio (o/e) 0.71, 90% interval 0.48 to 1.08. The upper end of that interval is the gene's LOEUF score, 1.08, which puts it in group 4 of 6, group 1 being the genes least tolerant of losing a copy. Missense variants: 243 observed, 293.43 expected, observed/expected ratio (o/e) 0.83, 90% interval 0.75 to 0.92. Synonymous variants: 136 observed, 120.47 expected, observed/expected ratio (o/e) 1.13, 90% interval 0.98 to 1.3.
Homologues: Orthologues: chimpanzee PATR-DMB (98% identical), macaque MAMU-DMB (89% identical), rabbit HLA-DMB (79% identical), dog HLA-DMB (77% identical), guinea pig HLA-DMB (76% identical), pig SLA-DMB (76% identical), rat RT1-DMb (72% identical), mouse H2-DMb2 (72% identical), mouse H2-DMb1 (71% identical), tropical clawed frog mhc2-dmb (30% identical). Paralogues in human: HLA-DQA2 (21% identical), HLA-DRB1 (21% identical), HLA-DPA1 (21% identical), HLA-DRB5 (21% identical), HLA-DPB1 (20% identical), HLA-DQA1 (20% identical), HLA-DRA (20% identical), HLA-DMA (19% identical), HLA-DOA (19% identical), HLA-DOB (19% identical), HLA-DQB2 (19% identical), HLA-DQB1 (19% identical), and 1 more.
Diseases named in the same sentence as HLA-DMB in open-access papers:
HLA-DMB is named in the same sentence as 63 diseases in open-access papers, as found by Europe PMC text mining. Sharing a sentence is not in itself a finding about the gene and the disease. The quoted sentences say what the papers report.
rheumatoid arthritis (6 papers, 2023 to 2024). A chronic, systemic autoimmune disorder characterized by inflammation in the synovial membranes and articular surfaces. "One DMP (cg22324029) was annotated to the HLA-DMB gene, which was previously linked to several autoimmune diseases, such as multiple sclerosis, rheumatoid arthritis, and type 1 diabetes." (PMID 37029435, 2023). "Polymorphisms in the HLA-DMB and HLA-DPA1 genes have been linked to autoimmune diseases like rheumatoid arthritis and psoriasis." (PMID 38835033, 2024). "We observed the distinct association between “severe COVID-19 or rheumatoid arthritis” with JIA that was mediated by a subset of 6p21.3 genes within cluster 8 (AGPAT1, PSMB8, TAP1, HCG4P11, HLA-DMB)." (PMID 39175752, 2024). "HLA-DMB is a prognostic factor in rheumatoid arthritis; however, its role in the processing of osteoarthritis has not been clarified yet." (PMID 36836601, 2023).
COVID-19 (5 papers, 2020 to 2024). A disease caused by infection with severe acute respiratory syndrome coronavirus 2. "Further, we investigated the expression of MHC class II molecules (MHCII) and Fc receptors (FcRs) and found that they were broadly upregulated in APCs in lungs of mild COVID-19 patients, with a MHCII subset (HLA-DRA, HLA-DMB, HLA-DRB1, HLA-DPB1, HLA-DQB1, HLA-DMA) were downregulated." (PMID 34502134, 2021). "Regarding the downregulated geneset, MHC II molecules, including HLA-DQA1, HLD-DRA, HLA-DRB1, HLA-DMB, HLA-DMA, etc., and cytokine/chemokine genes, including IL1B, TNF, CCL3, CCL4, and CXCL8 were expressed at lower levels in COVID-19 patients, especially those with severe diseases." (PMID 33101705, 2020). "In contrast, the expression of FCER1A, HLA-DMB, and CD1C was not different between severe COVID-19 and non-COVID-19 patients." (PMID 38262689, 2024).
Sepsis (5 papers, 2023 to 2025). Sepsis is defined as life-threatening organ dysfunction caused by a dysregulated host response to infection. "The qPCR data exhibited the same pattern of expression of these genes as the GSE65682 dataset, with IL4R and LTB4R being expressed at significantly higher levels in sepsis cases and HLA-DMB exhibiting the opposite trend (all P < 0.01)." (PMID 37033939, 2023). "Compared with healthy controls (n = 42), IL4R and LTB4R were significantly upregulated in sepsis patients (n = 479), while HLA-DMB was significantly downregulated (all P < 0.001)." (PMID 37033939, 2023). "In a separate study, a 14-dataset analysis of adult and pediatric sepsis spanning 8 different countries, the decrease of HLA-DMB expression in whole blood was observed soon after a sepsis diagnosis in the most severe cases." (PMID 37533854, 2023). "Patients with higher risk scores tended to express lower levels of LTB4R, HLA-DMB and IL4R, indicating that upregulation of the three IRGs was a favorable prognostic factor in sepsis." (PMID 37033939, 2023). "The expression of PDE4D in sepsis patients decreased continuously with time, and the low expression level of PDE4D was found to be related to HLA-DMA and HLA-DMB." (PMID 37834169, 2023). "Moreover, cytokine IL-10 inhibits the expression of Class II major histocompatibility complex (MHC) proteins (HLA-DR, HLA-DMA, and HLA-DMB) on the surface of macrophages and monocytes, which in addition to TGF-β, suppresses T-cell proliferation, contributing to immunosuppression in sepsis." (PMID 38235139, 2023).
serous ovarian cancer (5 papers, 2010 to 2024). "Increasing evidence suggests that the upregulation of HLA-DMB is associated with higher survival rates in advanced serous ovarian cancer and cervical cancer, although the mechanisms of action differ." (PMID 39917362, 2024). "HLA-DMB (− 69.7-fold) belongs to the major histocompatibility complex class II genes, and higher HLA-DMB expression was associated with higher survival rate via increased CD8 lymphocyte numbers in advanced-stage serous ovarian cancer." (PMID 33515271, 2021). "Tumor cell expression of HLA-DMB has been shown to correlate with an increased number of tumor-infiltrating CD8+ T lymphocytes, both of which are associated with improved survival in advanced serous ovarian cancer." (PMID 39917362, 2024). "Previous studies have confirmed that mRNA and protein levels of HLA-DMB are highly expressed in tumor samples from patients with advanced serous ovarian cancer with a large number of tumor-penetrating CD8 T lymphocytes, which can significantly prolong the median survival time." (PMID 32256213, 2020).
autoimmune disease (4 papers, 2023 to 2025). A disorder resulting from loss of function or tissue destruction of an organ or multiple organs, arising from humoral or cellular immune responses of the individual to their own tissue constituents. "The aberrant expression of HLA-DMB is associated with many diseases, including diabetes mellitus, autoimmune disease, infection, and cancer." (PMID 36936430, 2023). "However, whether HLA-DMB could exert similar roles in periodontitis as in other autoimmune diseases remains unclear." (PMID 40267082, 2025).
Kaposi's sarcoma (4 papers, 2016 to 2025). A malignant neoplasm characterized by a vascular proliferation which usually contains blunt endothelial cells. "HLA-DMB was reported as a candidate gene for Kaposi's sarcoma associated with AIDS complications through SNP screening." (PMID 33013899, 2020). "Polymorphisms in HLA-DMB antigen and SAPCD1, another class III MHC gene, at chromosome 6p21.3 had links to Kaposi sarcoma." (PMID 39885374, 2025).
type 1 diabetes (4 papers, 2011 to 2023). "Whereas in our pathway analysis, more genes are identified as part of Type I diabetes mellitus and Allograft rejection pathways (i.e. CD28, HLA-B, HLA-C, HLA-DMB, HLA-DPA1, HLA-DQA2, HLA-DRA, IL12A)." (PMID 22046267, 2011).
asthma (3 papers, 2021 to 2023). "The abnormal DNA methylation of HLA-DMB modified the gene expression and was associated with an increased risk of asthma, suggesting HLA-DMB is involved in human immune response." (PMID 37029435, 2023). "The decreased expression of HLA-DMB in allergic asthma tissue affected the maturation of T lymphocytes, thereby causing asthma." (PMID 34714718, 2021). "The expression of HLA-DMB was lower in the allergic asthma tissue, changing the maturation of T lymphocytes, thereby leading to the occurrence of asthma." (PMID 34714718, 2021). "Further analysis of HLA-DMB gene methylation, its differentially methylated site cg04933135, and T lymphocyte levels with respect to the occurrence of asthma." (PMID 34714718, 2021). "The methylation status of HLA-DMB gene in the blood samples of asthma patients and healthy controls was significantly different (P < 0.001)." (PMID 34714718, 2021). "The results showed that methylation of HLA-DMB was detected in 90.0% (27/30) of patients with asthma, and methylation was detected in 3.3% (1/30) of healthy volunteers." (PMID 34714718, 2021). "DNA methylation plays an important role in the development of asthma, and HLA-DMB which modified by abnormal DNA methylation can be regarded as a new biomarker of asthma." (PMID 34714718, 2021). "On the other hand, we analyzed the status of HLA-DMB methylation in the blood samples of asthma patients and healthy volunteers by MSP-PCR." (PMID 34714718, 2021). "In order to verify the results of bioinformatics analysis, we collected blood samples from asthma patients and healthy volunteers to detect the expression level of HLA-DMB mRNA and its DNA methylation status." (PMID 34714718, 2021). "As expected, the expression level of HLA-DMB mRNA in blood samples of asthma patients is lower than that of healthy people." (PMID 34714718, 2021). "In summary, DNA methylation plays an important role in the development of asthma, and HLA-DMB which modified by abnormal DNA methylation can be regarded as a new biomarker of asthma." (PMID 34714718, 2021). "Using blood samples from asthma patients, we confirmed that HLA-DMB expression is down-regulated, which may be affected by abnormal DNA methylation." (PMID 34714718, 2021). "Finally, we collected blood samples from asthma patients and healthy people, and detected the expression level of HLA-DMB mRNA and the methylation status of HLA-DMB." (PMID 34714718, 2021). "In addition, the un-methylation of HLA-DMB accounted for 10.0% and 96.7% of asthma patients (3/30) and healthy volunteers (29/30), respectively." (PMID 34714718, 2021). "Therefore, abnormal DNA methylation may be an important reason for the low expression of HLA-DMB in asthma." (PMID 34714718, 2021). "To date, no studies have reported on the relationship between CD3D, CD3G, RGS1, HLA-DMB, GBP4, GBP5, and asthma." (PMID 36118895, 2022). "RT-qPCR results showed that the expression level of HLA-DMB mRNA in the blood samples of asthma patients was significantly lower than that of healthy volunteers, indicating HLA-DMB is closely related to the occurrence of asthma." (PMID 34714718, 2021). "Gene ontology and Kyoto Encyclopedia of Genes and Genomes analyses showed that the differentially expressed genes, HLA-DMB, IL4, HLA-DPB1, and CD40LG, were related to the occurrence of asthma, and HLA-DMB expression was significantly reduced in allergic asthma." (PMID 34714718, 2021). "Our further analysis revealed that HLA-DMB has abnormal DNA methylation modification, which may be one of the main reasons for the low expression of HLA-DMB in asthma." (PMID 34714718, 2021). "However, no study has reported that abnormal methylation of the HLA-DMB gene promotes the maturation of T lymphocytes to trigger asthma." (PMID 34714718, 2021).
ovarian carcinoma (3 papers, 2010 to 2021). A malignant neoplasm originating from the surface ovarian epithelium. "Consistent with our findings, HLA-DMB expression in ovarian cancer epithelial cells was associated with CD8 T cell infiltration and a marked improvement in disease survival." (PMID 34834481, 2021).
AIDS (2 papers, 2020 to 2021). A syndrome resulting from the acquired deficiency of cellular immunity caused by the human immunodeficiency virus (HIV). "Most significantly, a SNP in the HLA‐DMB intronic region (NM_002118.4:c.55+649T>C, rs6902982) was associated with a four‐times higher risk of AIDS‐KS in HIV‐KSHV co‐infected men." (PMID 33043529, 2021). "Several variants identified in a SNP screening of the HLA‐DMB gene region were found to increase AIDS‐KS risk." (PMID 33043529, 2021).
diabetes (2 papers, 2023). "Consistently, one significant DMR (Chr 6, 32908239–32909282) also overlapped with the HLA-DMB gene, suggesting that the association between diabetes in pregnancy and the CpG site was robust." (PMID 37029435, 2023).
melanoma (2 papers, 2019 to 2024). A malignant, usually aggressive tumor composed of atypical, neoplastic melanocytes. "We further analyzed the prevalence of HLA-DMB mutations in various cancers and found that the tumors with the highest HLA-DMB mutation rates were diffuse large B-cell lymphoma (DLBC), melanoma (SKCM), colon cancer (COAD), and UCEC." (PMID 39917362, 2024).
viral infection (2 papers, 2018 to 2021). "As MHC class II protein complex is encoded by the human leukocyte antigen complex (HLA), HLA-DMB is under-expressed in both viral and bacterial infection, but by a greater magnitude in bacterial than viral infection." (PMID 34442377, 2021). "Based on known association between acute viral infection and the MHC region, it is reasonable to infer that more transcription of HLA‐DMA and HLA‐DMB (class II alleles) would correlate with higher anti‐CHIKV antibody titers, since they are involved in both the adaptive and humoral responses." (PMID 30150281, 2018).
acute myeloid leukemia (1 paper, 2022). Acute myeloid leukemia (AML) is a group of neoplasms arising from precursor cells committed to the myeloid cell-line differentiation. "Further, an in-depth literature analysis revealed that several of these genes play important roles in cancer (CDCA3, ECEL1, EN1, HLA-DMB, SPRR2A, TMEM40) including acute myeloid leukemia (CDCA3, HLA-DMB, RPL18A, PF4, PRG3) and T cell acute lymphoblastic leukemia (TLX3)." (PMID 35008420, 2022).
allergic asthma (1 paper, 2021). A asthma with a basis in a pathological type I hypersensitivity reaction. "HLA-DMB expression was significantly lower in patients with allergic asthma (p = 0.0275, log2FC = −1.12), cg04933135 correlated with HLA-DMB expression (p = 0.034), and cg04933135 was the site of differential methylation (corrected p = 0.041)." (PMID 34714718, 2021). "HLA-DMB expression was significantly decreased in allergic asthma, and the differentially methylated site cg04933135 positively correlated with HLA-DMB expression." (PMID 34714718, 2021).
cervical cancer (1 paper, 2024). A primary or metastatic malignant neoplasm involving the cervix. "Additionally, upregulation of the HLA-DMB gene has been linked to survival in cervical cancer patients." (PMID 39917362, 2024).
childhood asthma (1 paper, 2022). "Based on qRT-PCR validation, CD3D, CD3G, HLA-DMB, CD69, RGS1, and CIITA were shown to be upregulated in childhood asthma patients." (PMID 36118895, 2022). "Results showed that the mRNA levels of CD3D, CD3G, HLA-DMB, CD69, RGS1, and CIITA were significantly upregulated in childhood asthma patients compared with the control individuals." (PMID 36118895, 2022). "Results showed that the mRNA expression levels of CD3D, CD3G, HLA-DMB, CD69, RGS1, and CIITA were significantly upregulated in childhood asthma patients compared with healthy controls, consistent with bioinformatics analysis." (PMID 36118895, 2022).
colon adenocarcinoma (1 paper, 2024). "Moreover, among 19 Hub-MHCsig, HLA-DMA, HLA-DMB, and HLA-DOA were positively correlated with microsatellite instability in colon adenocarcinoma, while TAP2, TAP1, and HLA-F were negatively correlated with microsatellite instability in testicular germ cell tumors." (PMID 38714579, 2024).